NWD1 (NACHT and WD repeat domain containing 1)
Description:
May play a role in the control of androgen receptor (AR) protein steady-state levels.
Tractability: No criterion of Open Targets' tractability assessment is met for any kind of drug.
Gene: Protein-coding gene on chromosome 19 (16,719,847 to 16,817,963, forward strand). Ensembl gene ENSG00000188039.
Subcellular location: Cytoplasm, cytosol
Subcellular location (Human Protein Atlas): Cytosol; Nucleoli
Gene Ontology:
Biological process: intracellular signal transduction
Cellular component: cytosol
Genetic constraint (gnomAD): Loss-of-function variants: 116 observed, 127.23 expected, observed/expected ratio (o/e) 0.91, 90% interval 0.78 to 1.06. The upper end of that interval is the gene's LOEUF score, 1.06, which puts it in group 4 of 6, group 1 being the genes least tolerant of losing a copy. Missense variants: 1,638 observed, 1,810.3 expected, observed/expected ratio (o/e) 0.9, 90% interval 0.87 to 0.94. Synonymous variants: 725 observed, 772.39 expected, observed/expected ratio (o/e) 0.94, 90% interval 0.88 to 1.
Homologues: Orthologues: chimpanzee NWD1 (98% identical), macaque NWD1 (93% identical), dog NWD1 (83% identical), pig NWD1 (82% identical), mouse Nwd1 (77% identical), rat Sin3b (76% identical), guinea pig NWD1 (60% identical). Paralogues in human: WDR81 (16% identical), TEP1 (12% identical), MAPKBP1 (8% identical), WDR62 (8% identical), COP1 (7% identical), WDR27 (7% identical), WDR17 (6% identical), AHI1 (6% identical), WDR7 (5% identical), DAW1 (5% identical), WDR75 (5% identical), PAFAH1B1 (4% identical), and 14 more.
Diseases named in the same sentence as NWD1 in open-access papers:
NWD1 is named in the same sentence as 19 diseases in open-access papers, as found by Europe PMC text mining. Sharing a sentence is not in itself a finding about the gene and the disease. The quoted sentences say what the papers report.
prostate carcinoma (4 papers, 2014 to 2023). A carcinoma that arises from epithelial cells of the prostate gland. "We determined that expression of NWD1 becomes elevated during prostate cancer progression, based on analysis of primary tumor specimens." (PMID 24681825, 2014). "We discovered that both mRNA and protein levels of NWD1 are elevated during prostate cancer pathogenesis or progression." (PMID 24681825, 2014). "NWD1 knockdown potently suppressed growth of androgen-dependent LNCaP prostate cancer cells, thus showing its functional importance in an AR-dependent tumor cell model." (PMID 24681825, 2014). "NWD1 (NACHT and WD repeat domain-containing 1) modulates androgen receptor signaling in prostate cancer." (PMID 38203246, 2023). "The so far only function reported for NWD1, first identified in the zebrafish genome as NACHTP1, is its involvement in androgen signalling in the context of prostate cancer." (PMID 27248802, 2016).
autism spectrum disorder (1 paper, 2025). A spectrum of developmental disorders that includes autism, and Asperger syndrome. "The NWD1 (NATCH and WD repeat domain containing 1) gene, located on chromosome 19p13.11, has been implicated in hormone-related cancers (ovarian, breast, prostate) and autism spectrum disorder, suggesting a role in tumorigenesis and neurodevelopment." (PMID 40236422, 2025).
depression (1 paper, 2022). "These genes include CHD7, ADCY3, ANK3, NWD1, CNTNAP2 and TSNAX-DISC1, each of which has been carefully considered and contrasted as no previous link between neural disorders or psychiatric conditions, including depression, has been made for risk preference." (PMID 34696705, 2022).
kidney calculus (1 paper, 2025). "For instance, NWD1 is suggestively associated with kidney calculus (P value = 7.53 × 10−7, OR = 1.63) in the UTR plus protein-coding PheWAS, but not in the protein-coding-alone or the UTR-alone collapsing PheWASs." (PMID 40770095, 2025).
lung adenocarcinoma (1 paper, 2020). A carcinoma that arises from the lung and is characterized by the presence of malignant glandular epithelial cells. "For lung adenocarcinoma, we found that the expression levels of three genes, GPR15, HDGF, and AHHR, were associated with increased smoking-related mutational signature, while an inverse association was observed for the other four genes, NWD1, KCNQ1, CAPN8 and RPS6KA1." (PMID 32928150, 2020).
lung carcinoma (1 paper, 2025). "Notably, several of these CpG sites (SNORD93, NWD1, EDC3) have been associated with COPD33, which is an established independent risk factor for lung cancer in both smokers and never smokers." (PMID 40236422, 2025).
periventricular nodular heterotopia (1 paper, 2020). Periventricular nodular heterotopia (PNH) is a brain malformation, due to abnormal neuronal migration, in which a subset of neurons fails to migrate into the developing cerebral cortex and remains as nodules that line the ventricular surface. "Downregulation of Nwd1 by shRNA expression in the embryonic cerebral cortex often caused the cortical dysgenesis similar to human periventricular nodular heterotopia (PH), a cortical malformation that is characterized by the formation of ectopic aggregates of neurons that line the lateral ventricle." (PMID 32344379, 2020).
prostate tumors (1 paper, 2014). "Increased levels of NWD1 immunostaining were found in samples of prostate tumors resistant to androgen deprivation therapy (n=20)." (PMID 24681825, 2014). "A relative increase in NWD1 expression at the mRNA level could also be inferred for stage III prostate tumors but due to the limited number of samples tested (also for stages I and IV), no statistical difference could be assumed." (PMID 24681825, 2014).
schizophrenia (1 paper, 2022). A major psychotic disorder characterized by abnormalities in the perception or expression of reality. "NWD1 (NACHT and WD Repeat Domain Containing 1) is a protein coding gene in which mutations have previously been linked to schizophrenia." (PMID 34696705, 2022).
Seizure (1 paper, 2020). A seizure is an intermittent abnormality of nervous system physiology characterized by a transient occurrence of signs and/or symptoms due to abnormal excessive or synchronous neuronal activity in the brain. "Using a mouse model of acute epileptic seizures, it was suggested that Nwd1 regulates the neuronal hyperexcitability of glutamatergic synaptic transmission in the adult brain." (PMID 32344379, 2020).
temporal lobe epilepsy (1 paper, 2020). A localization-related (focal) form of epilepsy characterized by recurrent seizures that arise from foci within the temporal lobe, most commonly from its mesial aspect. "Although inactivating mutations in the human NWD1 gene have not been reported to date, it was recently shown that the neuronal expression of NWD1 is upregulated in patients with temporal lobe epilepsy." (PMID 32344379, 2020).
tumor (3 papers, 2014 to 2023). "Altogether, these data suggest a role for tumor-associated over-expression of NWD1 in dysregulation of AR signaling in PCa." (PMID 24681825, 2014). "High expression of NWD1 (median cut-off) was associated with areas of AR positive immunostaining in 75% of hormone refractory tumor samples (15/20)." (PMID 24681825, 2014). "Consistently, a previous study suggested a possible role for Nwd1 in tumor cells endowed with stem-cell-like properties; i.e., the proliferative and self-renewing properties." (PMID 32344379, 2020). "To verify the consistency of the RNA expression data with the respective protein yields, we generated polyclonal antibodies against NWD1 to further evaluate protein levels in prostatectomy samples containing tumor tissue representing different Gleason grades." (PMID 24681825, 2014). "The dependence of PDEF expression on NWD1 in a variety of tumor cell lines therefore suggests another connection of NWD1 to AR signaling pathways." (PMID 24681825, 2014). "No apparent changes in the levels of AR translocated to the nucleus were observed after NWD1 over-expression This direct correlation between NWD1 and AR protein levels is consistent with our observations in PCa tumor samples." (PMID 24681825, 2014). "An increase in NWD1 expression could be observed, particularly when comparing normal tissues (n=7) versus stage II tumor samples (n=19)." (PMID 24681825, 2014). "For instance, FOXA1, NWD1 and MAZ have been shown to promote tumor progression by modulation of androgen receptor expression and are frequently linked with poor prognosis." (PMID 36818049, 2023). "In fact, stage II tumor samples with assigned Gleason score and reported TNM (n=7) showed an increase of 5-fold (p<0.0001) in NWD1 mRNA expression levels when compared to normal prostate tissues." (PMID 24681825, 2014). "Under basal conditions, no major changes in cell proliferation or cell migration in vitro (wound healing assay) or tumor development in mouse xenografts (using 7 week-old female nude mice) were noticed when silencing NWD1, using PPC-1 as cellular model (data not shown)." (PMID 24681825, 2014).
cancer (2 papers, 2014 to 2021). A tumor composed of atypical neoplastic, often pleomorphic cells that invade other tissues. "According to the differential expression profile that was generated and analyzed by the Ingenuity PathwaysTM software (IPA version 7.1, Ingenuity Systems), NWD1 is presumably associated with biological networks related to tissue morphology, organogenesis, cancer and neurological diseases." (PMID 24681825, 2014).
adenocarcinoma (1 paper, 2014). A common cancer characterized by the presence of malignant glandular cells. "Although barely expressed in Gleason grade G2 adenocarcinoma (n=11), NWD1 was significantly up-regulated in G3 (n=166) (p<0.0001), G4 (n=68) (p<0.0001), and G5 (n=8) (p<0.0001) PCa specimens compared to the normal prostate glands." (PMID 24681825, 2014).
respiratory diseases (1 paper, 2025). "Previously identified smoking-related CpG sites that were also linked to smoky coal combustion – annotated to genes such as AHRR, SNORD93, NWD1, EDC3, STK24, ZDHHC14, HIF3A – converge on key pathways involved in pollutant response, respiratory diseases, and carcinogenesis." (PMID 40236422, 2025).
NWD1 also shares sentences with these, for which no sentence is quoted: neurological diseases (2 papers); benign prostatic hyperplasia (1); endometrial cancer (1); glaucoma (1).